RNU2-54P (RNA, U2 small nuclear 54, pseudogene)
Gene: Small nuclear RNA gene on chromosome 8 (76,265,543 to 76,265,732, reverse strand). Ensembl gene ENSG00000222231.
Homologues: Orthologues: chimpanzee U2 (96% identical), macaque U2 (94% identical), mouse Gm24037 (61% identical). Paralogues in human: RNU2-23P (76% identical), RNU2-59P (75% identical), RNU2-36P (74% identical), RNU2-14P (74% identical), RNU2-2 (73% identical), U2 (73% identical), U2 (72% identical), RNU2-48P (72% identical), RNU2-3P (71% identical), RNU2-52P (71% identical), RNU2-8P (71% identical), RNU2-32P (70% identical), and 65 more.